FAM180A (family with sequence similarity 180 member A)
Synonyms: HWKM1940; UNQ1940
Tractability: Antibody: UniProt places it where antibodies can reach, with high confidence; UniProt predicts a signal peptide or a membrane-spanning region; its Gene Ontology location is reachable by antibodies, with medium confidence.
Gene: Protein-coding gene on chromosome 7 (135,728,348 to 135,748,813, reverse strand). Ensembl gene ENSG00000189320.
Subcellular location: Secreted
Subcellular location (Human Protein Atlas): Vesicles; Predicted to be secreted
Gene Ontology:
Cellular component: extracellular region
Genetic constraint (gnomAD): Loss-of-function variants: 13 observed, 14.67 expected, observed/expected ratio (o/e) 0.89, 90% interval 0.58 to 1.41. The upper end of that interval is the gene's LOEUF score, 1.41, which puts it in group 5 of 6, group 1 being the genes least tolerant of losing a copy. Missense variants: 198 observed, 227.96 expected, observed/expected ratio (o/e) 0.87, 90% interval 0.77 to 0.98. Synonymous variants: 90 observed, 100.05 expected, observed/expected ratio (o/e) 0.9, 90% interval 0.76 to 1.07.
Homologues: Orthologues: chimpanzee FAM180A (99% identical), macaque FAM180A (97% identical), guinea pig FAM180A (84% identical), dog FAM180A (83% identical), pig FAM180A (83% identical), rat Fam180a (80% identical), mouse Fam180a (79% identical), rabbit FAM180A (75% identical), tropical clawed frog FAM180A (50% identical), zebrafish FAM180A (32% identical). Paralogues in human: FAM180B (23% identical).
Diseases named in the same sentence as FAM180A in open-access papers:
FAM180A is named in the same sentence as 2 diseases in open-access papers, as found by Europe PMC text mining. Sharing a sentence is not in itself a finding about the gene and the disease. The quoted sentences say what the papers report.
tumor (1 paper, 2025). "FAM180A is identified as a potential marker for tumor microenvironment phenotype prediction and is closely linked to personalized prognosis." (PMID 40989695, 2025). "FAM180A, as one of the candidate proteins for personalized prognosis and tumor microenvironment phenotypes prediction in tumors, was highlighted as well." (PMID 40989695, 2025).
FAM180A also shares sentences with these, for which no sentence is quoted: systemic sclerosis (1 paper).